NOTCH1 (notch receptor 1)
Diseases named in the same sentence as NOTCH1 in open-access papers (continued):
Sharing a sentence is not in itself a finding about the gene and the disease.
tumor (continued). "Moreover, we measured the expression levels of apoptosis, autophagy‐related proteins, and Notch1 pathway in these tumor samples." (PMID 37409635, 2023). "Importantly, we determined that the mechanism by which chemotherapy treatment enhances MenaINV expression occurs also through increased macrophage recruitment and subsequent cooperative Notch1 and NF-κB signaling in tumor cells." (PMID 37024946, 2023). "In contrast, NOTCH1 has a tumor-suppressor role in the pathogenesis of OSCC." (PMID 37445908, 2023). "In fact, to date, almost all Notch1 inhibitors have largely failed in their clinical management due to gastrointestinal toxicities, non-selective Notch inhibition, and effective therapeutic doses to curb tumor growth." (PMID 36909163, 2023). "When MDA-MB-231 cells were treated with the Notch-1 siRNA and miRNA mimics, miRNA levels were changed, Notch signaling-related proteins were reduced, and tumor survival, invasion, and angiogenesis were decreased, suggesting that Luteolin inhibited Notch signaling by regulating miRNAs." (PMID 36992138, 2023). "Human EGFR, Notch1, Notch2, and Notch3 mRNA were all expressed in tumours." (PMID 37441599, 2023). "Depending on the cellular context, NOTCH1 signaling may have controversial functions and be both oncogenic and tumor-suppressive." (PMID 37833915, 2023). "This suggests that proinflammatory cytokines, such as TNF-α, produced in response to tumor growth and circulating through the bloodstream may enforce endothelial Notch1 signaling at distant sites." (PMID 37749321, 2023). "Notch1 signaling pathway is known to act as a tumor suppressor in IDH‐DGIIG." (PMID 37533228, 2023). "The intensity of the Notch1 stain appears to be directly proportional to the grade of the tumour." (PMID 37489207, 2023). "As a sarco-endoplasmic reticulum Ca2+-ATPase (SERCA) modulator, thapsigargin may inhibit oncogenic NOTCH 1 signaling, thereby possibly suppressing tumor growth." (PMID 37600972, 2023). "It was also reported that high expression levels of NOTCH1 mRNA in the tumor tissues correlate with improved patient outcomes and longer survival, which seemed to contribute to a tumor-suppressor-like function of the Notch pathway, which is lost by alterations of this." (PMID 37143088, 2023). "The intensity of the Notch1 stain appears to be directly proportional to the grade of tumour." (PMID 37489207, 2023). "NOTCH1 target genes are also associated with the control of apoptosis, epithelial–mesenchymal transition (EMT), increased drug resistance, modulation of the tumour microenvironment, and maintenance of the cancer stem cell population." (PMID 37628760, 2023). "Indeed, forced expression of miR-138–2 suppressed the tumor growth in vivo along with a significant down-regulation of NOTCH1, MAML1, APH1A and HES1." (PMID 36973704, 2023). "Clearly, NOTCH1 is expected to have dual roles as both a tumor suppressor and an oncogene." (PMID 36879115, 2023). "We previously created ligand-specific inhibitors of Notch signaling comprised of Fc fusions to specific EGF-like repeats of the Notch1 extracellular domain, called Notch decoys, which bound ligands, blocked Notch signaling, and showed anti-tumor activity with low toxicity." (PMID 36376768, 2023). "This may offer a potential therapy targeted against the Notch signalling pathway in tumours that strongly express Notch1." (PMID 37489207, 2023). "The expression of markers associated with lineage and cell differentiation was associated with histotype rather than the Notch1 or 2 status of a tumour." (PMID 37686600, 2023). "If chemotherapy fails to eradicate the tumor completely, an increased density of TAMs may subsequently enhance NF-κB signaling, which combined with Notch1 signaling, will increase MenaINV expression in residual tumor cells." (PMID 37024946, 2023).
tumor (continued). "In addition, CBL0137 also inhibits the self-renewal of cancer stem cells or tumor-initiating cells via NOTCH1 activation." (PMID 36691066, 2023). "NOTCH1 has been proven to have both oncogenic and tumor suppressor activities." (PMID 37629093, 2023). "Therefore, we studied the combinatory effect of tumor differentiation and NOTCH1 expression on OSCC morality." (PMID 37859809, 2023). "Interestingly, CAF states 2 and 3 (inflammatory/adipogenic CAFs) were shown to mediate crosstalks with tumor endothelial cells notably via NOTCH1/2/3_JAG1/2/DLL4 pathways reiterating the role of NOTCH signaling in CAF-mediated angiogenesis." (PMID 38269089, 2023). "In vitro and in vivo, chrysin may reduce the proliferation and induce the apoptosis and death of cells, reduce inflammation, and inhibit tumor growth by activating the Notch1 signaling pathway." (PMID 36969872, 2023). "Mechanistically, GNA14 likely controls the retinoblastoma pathway by inducing Notch1 cleavage to stop tumor growth, and it may also prevent tumor cell migration by suppressing the expression of Jumonji domain-containing 6 (JMJD6)." (PMID 38304027, 2023). "To validate NOTCH1 rearrangements, we performed RNA sequencing of all tumours." (PMID 37749094, 2023). "Intriguingly, our further investigation indicated that the pro-tumor effects of Notch1 might be tightly correlated with tumor-specific cell senescence and nutrition metabolism." (PMID 35585515, 2022). "We reasoned that NUMB might mediate isoform-specific effects through the distinct regulation of Notch1 activity in tumor cells." (PMID 35457181, 2022). "Treatment of tumor-bearing mice with AL101 led to significant responses in PDX models with activating NOTCH1 mutations but not in models with WT NOTCH genes." (PMID 35931701, 2022). "Similarly, all studied SNHGs are involved in EMT through activation of various athways including Notch-1, but in vivo experiments reveal a more crucial role in tumor growth and metastasis for SNHG1, SNHG3, SNHG5, SNHG12, and SNORA71A." (PMID 36139687, 2022). "Moreover, the relative contribution of Notch1 and Notch2 receptors to the tumor-suppressive activity of Notch signaling in this context remains elusive." (PMID 36358826, 2022). "Our work described for the first time a critical immunosuppressive pathway linking A2AR, Cbl-b and Notch1, which could represent a new functional immune-checkpoint that modulates T-cell responses in the tumor microenvironment." (PMID 36090975, 2022). "The correlations of NOTCH1 and tumor immune infiltration were also analyzed in ESCC." (PMID 36119057, 2022). "This was paralleled by a significant decrease in NOTCH-1 and TGF-β expression at p.i. day 1, and a slight increase in C/EBP-β, a senescence marker often associated with an increased risk of tumor development." (PMID 35075119, 2022). "The relative contribution of Notch1 and Notch2 receptors to the tumor-suppressive activity of Notch signaling in this context is unknown." (PMID 36358826, 2022). "To further investigate whether NOTCH1 involved in MET relied and M2 macrophage directly induced tumor cell planting, we intralung injected adenovirus targeted NOTCH1 to inhibit NOTCH1 expression." (PMID 36439868, 2022). "miR-30c acts as a tumor suppressor gene by targeting Notch1 at the posttranscriptional level." (PMID 36180477, 2022). "Here we provide evidence of how mutated NOTCH favors immune escape of tumor B cells and we address how CLL cells with trisomy 12 may provide a selective advantage for NOTCH1-mutations." (PMID 36266281, 2022).
tumor (continued). "Previously, miR-34a was reported to inhibit tumor angiogenesis in endothelial cells, and the neurogenic locus notch homolog protein 1 (Notch1) pathway has been reported to play an important role in vascular endothelial growth factor (VEGF)-treated angiogenesis." (PMID 36386230, 2022). "To date, many preclinical studies evaluated the anti-tumor effect of NOTCH1 inhibition." (PMID 35881043, 2022). "Therefore, activation of Notch1 in CML cells by PON can be considered as the ‘on‐target effect’ on the tumour." (PMID 35122387, 2022). "FBXW7 is a tumor suppressor gene encoding a subunit of the Skip1–Cull–F–box (SCF) ubiquitin ligase complex, which controls proteasome–mediated degradation of various cell cycle regulators such as cyclin E, c–Myc, Notch1, and mTOR." (PMID 36497403, 2022). "Therefore, although these data need further investigation, our observations confirm that Crenigacestat selectively targets NOTCH1 and that the desmoplastic response in iCCA likely plays a key role in both drug effectiveness and tumor progression." (PMID 35457006, 2022). "Notch1 is known to be the most important tumor suppressor in cSCC and thus could serve as a prognostic and diagnostic marker." (PMID 35956111, 2022). "Likewise, in human medullary thyroid cancer (MTC) tumor samples, NOTCH1 protein is undetectable, while the expression of NICD1 inhibits MTC cell proliferation." (PMID 35332121, 2022). "Moreover, BTBD7 inhibits BC cell proliferation, invasion, migration, and tumor metastasis by inactivating the Notch1 pathway." (PMID 35655918, 2022). "Notch1 expression is variable, depending on the anatomic region affected and the tumor histology." (PMID 35956111, 2022). "The immunomodulatory treatment with imiquimod upregulated the expression of NOTCH1 in tumor cells." (PMID 36430344, 2022). "Our work, together with previous studies, supports the idea that therapies that reactivate Notch1 in T-cells could be used to tune T-cells against tumor-induced immunosuppression and enhance anti-cancer immune responses." (PMID 36090975, 2022). "In the current study, we tested the hypothesis that the pan-class I PI3K/mTOR antagonist bimiralisib would result in cancer cell apoptosis and concomitant tumor shrinkage in NOTCH1-mutant HNSCC." (PMID 36124629, 2022). "MiR-326 is considered to be a tumor suppressor in several human cancers, since it could directly target downstream oncogenes, such as cyclin D1, phox2a, and Notch1." (PMID 35012553, 2022). "The results from both the N1fl/flPKC and the N1+/−PKC GEMMs were consistent, regardless whether Notch1 was either completely deleted in the tumor cell compartment alone or heterozygous inactivated in both the tumor and tumor microenvironment." (PMID 36970723, 2022). "Notch1 and Notch3 were associated with TNBC pathogenesis or etiology, malignant or aggressive phenotypes, while Notch4 levels are important for promoting mesenchymal signature and keeping prostemless signaling constant during tumor progression of TNBC." (PMID 36017236, 2022). "SPC25 functions as an oncogene related to the regulation of tumor cell stemness to promote HCC progression via the DNA-PK/AKT/Notch1 pathways whose detailed relationships remain to be determined and blockade of these pathways suppressed the tumorigenic effect induced by SPC25 upregulation." (PMID 36147467, 2022).
tumor (continued). "Furthermore, we found that JAG1 and NOTCH1 silencing decreased the in vivo OSCC tumor burden and tumor weight, respectively." (PMID 35249111, 2022). "It would be interesting to determine whether Notch3, which represses the proliferation of adult NSCs, contributes to the tumor suppressor activity of RBP-Jk in cooperation with Notch1 and Notch2." (PMID 36358826, 2022). "In all three NOTCH1-mutated T-ALL PDX models, OxPhos-i/VXL produced a profound reduction of spleen size, spleen weight (p < 0.0001), and tumor burden reduction in PB, spleen, and BM." (PMID 35589701, 2022). "Notch1 plays a tumor-suppressive role in CML and might have the potential to be used as a diagnostic marker along with other factors in CML patients." (PMID 35847841, 2022). "Similarly, miRNA-199, miRNA-214, and miRNA-3178 inhibit EMT alteration, TNBC cell proliferation, invasion, and metastasis by direct downregulation of the NOTCH1 gene that is supposed to be a key driver in terms of tumour cell initiation signalling." (PMID 36267139, 2022). "Taken together, we could draw a deduction that DNA-PK, AKT, and Notch1 signaling pathways might be the critical mechanism that promoted the tumor growth and progression in HCC cells with SPC25 upregulation." (PMID 36147467, 2022). "Inactivation of NOTCH1, as a tumor suppressor gene, may inhibit the Wnt/β-catenin signaling pathway, which is associated with cell polarity and differentiation." (PMID 35911687, 2022). "Furthermore, previous studies have demonstrated the oncogenic potential of NOTCH1 variants is heavily dependent on the type of tumor, with some cancers suggesting NOTCH1 is an oncogene and others more consistent with a tumor suppressor gene." (PMID 35186194, 2022). "NOTCH1 signaling shapes the tumor immunity in several cancer entities." (PMID 35205828, 2022). "Recently, the Notch1 pathway was also shown to be involved in drug resistance in tumor cells." (PMID 36297616, 2022). "Laminin treated tumor tissues also revealed enhanced expression of Notch1 in vivo." (PMID 35585515, 2022). "Additionally, NOTCH activation in ECs promotes lung metastasis, while endothelial NOTCH1 activation in the liver reduces intercellular adhesion molecule-1 expression and endothelial tumor cell adhesion and retention, thereby reducing liver metastasis." (PMID 35332121, 2022). "In addition, some investigations reported aberrant NOTCH1 in iCCA tissue, contributing to tumor growth." (PMID 35457006, 2022). "Inactivation of Rbpj, Notch1, or Notch2 receptors accelerates tumor growth in a mouse model." (PMID 35332121, 2022). "Additionally, in the presence of TGFβ in the TME, NOTCH1 and ZEB1 cooperate and jointly cause inhibition of NOTCH3 expression, which consequently promotes tumour initiation and EMT." (PMID 34944837, 2021). "A higher percentage of nuclear NICD (intracellular portions of NOTCH1)-positive cells was observed in tumor samples of CREBBPmut/EP300mut patients than those of CREBBPwt/EP300wt patients, confirming the link of CREBBP/EP300 mutations with NOTCH signaling activation." (PMID 33431788, 2021). "Next, we tested whether glycolysis plays a role in Notch1/TAZ axis-mediated regulation of tumor growth in nude mice." (PMID 34482375, 2021). "The determined tumor area upon Notch1 knock-out was slightly decreased from 24.68 to 17.90% (p = 0.1672) as well as tumor cell proliferation, indicated by the KI67 index, from 21.00 to 17.86% (p = 0.3034) in a dose-dependent manner, though not significantly, comparing R+ N1w/w and R+ N1f/f mice." (PMID 34257546, 2021).
tumor (continued). "Therefore, by sponging miR-34a, circ-ASH2L enhanced the expression of Notch1, one of the oncogenic signals, leading to tumor progression and poor survival of patients with pancreatic cancer." (PMID 34439315, 2021). "Besides, miR-34a delivery has remarkably downregulated the expression of Notch1, inhibit tumor migration, and decrease the tumor size and volume in mice bearing MDA-MB-231 cells." (PMID 34440380, 2021). "In addition, the presence of a subcutaneous tumor in mice can over-activate Notch1 signaling, not only in ECs within the tumor, but also at sites as distant as the lungs." (PMID 34073394, 2021). "To test whether the downregulation of EGFR in tumor spheres was dependent on the activation of Notch1, we performed binding assays of parental cells (H1975 and HCC827) to plates coated with an increasing concentration of the DLL4 Notch agonist." (PMID 33922104, 2021). "In addition, combining chemotherapy which inhibits bulk tumor with Notch1 and GLI1 inhibitors that abrogate stemness display an excellent synergy in inhibiting AA-TNBC, hence providing a potent therapeutic option for abrogating TNBC in AA women." (PMID 34889737, 2021). "In particular, the tumor sensitization to 5-FU by Notch1 knockdown was mediated through p27 upregulation, and inhibition of Notch1 by DAPT affected the 5-FU-chemoresistant population of CRC cells to a higher extent compared with the parental one through targeting the pool of CSC." (PMID 34680255, 2021). "Linc-OIP5 induces proliferation and migration through NOTCH1 (Notch homolog 1, translocation-associated), YAP (yes-associated protein 1), JAG1 and HES1 (hairy and enhancer of split-1) and downregulating its expression reduced tumor growth in vivo." (PMID 34316694, 2021). "Additionally, the ADAM17 inhibitor ZLDI-I, by preventing 5-FU-mediated upregulation of Notch1-4, improved the anti-tumor activity of 5-FU and reversed EMT, acting in a synergic or additive way in different concentrations." (PMID 34680255, 2021). "In summary, NOTCH1 proficiency plays an important role for the colonization of the PVN and tumor growth, whereas its deficiency results in impaired growth but also induces TM- and network formation that makes the tumor more radioresistant." (PMID 33579922, 2021). "High expression of Notch1 indicates higher differentiation, while increased expression of Notch4 may indicate a lower degree of differentiation and possibly a tumor with more aggressive function." (PMID 36643842, 2021). "Notch1 deficiency resulted in a mosaic-like pattern and complete loss of NICD1 in R+ N1f/w and R+ N1f/f mice, resulted in papillary ADCs comprised of cuboidal and columnar tumor cells, respectively." (PMID 34257546, 2021). "Other interactions have also been observed, such as Notch1 on CTCs with its ligand Jagged1 expressed on G-MDSCs, that might contribute to the neutrophil–tumor cell synapse required for the intime interaction between the two cell types." (PMID 34572138, 2021). "Likewise, in the same cancer, an LSD1 inhibitor, ORY1001, favored Notch1 expression and suppressed tumor growth in vitro and in vivo through Notch-dependent ASCL1 repression." (PMID 34680255, 2021). "Surprisingly, in silico analysis revealed a high degree of similarity of the VAV1−/− tumor transcriptome with that found deregulated in leukemic cells generated after ectopic expression of the intracellular domain of Notch1 (ICN1) in mouse bone marrow progenitors." (PMID 34571765, 2021). "It was observed that Notch1 may specifically bind to soluble E-cadherin (sE-Cad) and Trombospondin-1 (Thbs) and that these proteins are released from tumor cells when Notch1 is targeted." (PMID 33430387, 2021). "Western blotting confirmed that DBZ reduced the levels of the active NOTCH1 (cleaved NOTCH1) and its target HES1 protein and that Erlotinib lowered the EGFR phosphorylation level in H3118 xenografts, suggesting that tumor suppression was caused by on-target effects of each drug." (PMID 33473104, 2021).